INS (insulin)
Diseases named in the same sentence as INS in open-access papers (continued):
Sharing a sentence is not in itself a finding about the gene and the disease.
Insulin resistance (continued). "Since systemic insulin resistance and specific reduction of insulin sensitivity in major metabolic tissue could be induced in a short time, diet-induced diabetic BLTW : CD1(ICR) mice could be an efficient model for medical research with an advantage of ruling out strain-specific gloss." (PMID 22778782, 2012). "However, under insulin resistance conditions, despite the chronic peripheral hyperinsulinemia, downregulation of brain insulin synthesis and/or transport decreased brain insulin levels and its subsequent signaling cascades, culminating in increased Aβ levels, as in Tg2576 AD transgenic mice." (PMID 22500228, 2012). "In this study, using the insulin resistance animal model (rats fed high-fructose diet), we tested the hypothesis whether the combined administration of these agents could increase the efficacy of insulin action and whether a synergistic effect may occur." (PMID 23065486, 2012). "Insulin may be required as a growth factor during the catch-up growth phase, so the observation of a dose-dependent increase should be viewed as more than just compensation for GH-induced insulin resistance." (PMID 23116291, 2012). "In summary, our data suggests that exposure to a combination of dietary ASP and MSG may promote an increase in body weight, adiposity and markers of developing insulin resistance, including fasting blood glucose elevations and impairment in insulin sensitivity." (PMID 22697049, 2012). "However, increased hepatic insulin resistance was observed in 3 month-old obB1B2KO mice while the islets from obB1B2KO at the same age were able to secrete more insulin, overlapping any possible difficulty in glucose uptake caused by the KO of the kinin receptors." (PMID 22829877, 2012). "Components of the insulin-IGF axis have been key targets to identify potential biomarkers of adenoma risk, in part because western diets, physical inactivity and other factors associated with obesity, insulin resistance and diabetes history, are known risk factors for colon cancer." (PMID 22950808, 2012). "Although the pathogenesis of insulin resistance remains unclear, abnormal insulin signaling, mitochondrial dysfunction, endoplasmic reticulum (ER) stress, dysfunctional triglyceride/free fatty acid cycle intermediates, and inflammation have been reported to be involved in mediating this disease." (PMID 22110478, 2012). "Thus, it is not surprising that an acute increase in peripheral insulin levels leads to higher CSF insulin, whilst chronic peripheral hyperinsulinemia (as occurs in insulin resistance) downregulates insulin receptors (IR) at BBB, impairing insulin transport into the brain." (PMID 22500228, 2012). "Indeed, increases in reactive oxygen species levels may precede the onset of insulin resistance and lead to diminished insulin action, and lipid peroxidation, inflammation and cellular injury." (PMID 22615952, 2012). "The in vitro evaluation of compounds that can affect insulin resistance in myotubes has long been performed by measuring the changes in uptake of radiolabeled glucose analogs and/or in the expression and phosphorylation of components of the insulin signaling pathways." (PMID 22409911, 2012). "Moreover, few studies have analysed HOMA-IR, a more direct measure of insulin resistance, which can only be computed using fasting insulin and glucose values, and which has been shown to reflect insulin resistance assessed by the euglycaemic clamp more accurately than fasting insulin alone." (PMID 22127286, 2012). "However, activin A and/or activin B were positively correlated with parameters of insulin resistance and T2D, including fasting glucose (P < 0.001), fasting insulin (P = 0.02), glycated hemoglobin (P = 0.003), and homeostasis model assessment of insulin resistance (HOMA-IR; P < 0.001)." (PMID 23304117, 2012).
Insulin resistance (continued). "Although fasting serum insulin itself remains controversial as an indicator of insulin resistance, indices based on both fasting glucose and insulin (e.g. HOMA and QUICKI) may have more validity; more studies are needed before the same can be said of similar indices derived from saliva." (PMID 23781305, 2012). "Chronic rapamycin treatment may also impair insulin action via the inhibition of mTORC1-dependent mitochondrial biogenesis and activity, which could result in a buildup of lipid intermediates that are known to trigger insulin resistance." (PMID 22973301, 2012). "Other studies showed that intracerebroventricular administration of insulin was more efficient at reducing food intake and body weight in 3-month-old rats than in 8- and 24-month-old rats, indicating the development of hypothalamic insulin resistance with age in Wistar rats." (PMID 22675349, 2012). "Our observations are consistent with these findings and indicate that the decreased insulin sensitivity observed following FTox-G50 injection is mediated by an increase in the TNF-α concentration in adipose tissue, which selectively stimulates the expression of Map4k4 to cause insulin resistance." (PMID 22816003, 2012). "In addition, mice with germline heterozygous deletion of the gene encoding PPARγ resulting in reduced PPARγ activity exhibited increased insulin sensitivity as compared to wild-type mice and were also resistant to high-fat diet-induced obesity and insulin resistance." (PMID 22745632, 2012). "Interestingly, when the rapamycin pre-treatment was extended to 48 h, the myotubes became almost completely unresponsive to insulin stimulation, consistent either with further antagonism of lipid-induced insulin resistance via inhibition of mitochondria, or with disruption of mTORC2." (PMID 22973301, 2012). "However, as the number of youth with T2DM steadily increased over time, it was evident that some children were lean with minimal signs of insulin resistance such as acanthosis nigricans, but biochemically they had higher glucose levels, higher haemoglobin A1Cs, and lower serum insulin levels." (PMID 22288007, 2012). "Other than an enhancement of glucose uptake, Akt phosphorylation also involves in GSK3-dependent pathway which responsible for glycogen synthesis and it was reported that HCV-induced insulin resistance may be through impairment of insulin-induced GSK3β phosphorylation." (PMID 22721429, 2012). "However, some attention needs to paid to the interpretation of these values as indices of insulin resistance because they mainly depend on the balance between hepatic glucose output and insulin secretion, which is maintained by a feedback loop between the liver and pancreatic β-cells." (PMID 23249601, 2012). "Because the liver, an important target organ of insulin, plays a critical role in regulating metabolism, patients with chronic liver diseases often suffer from several nutritional and metabolic disorders, such as protein-energy malnutrition and insulin resistance." (PMID 22312273, 2012). "In order to develop logical and novel approaches for treating and preventing neurodegeneration based on the brain insulin resistance hypothesis, three main questions must be addressed: 1) Do T2DM and other peripheral insulin resistance states cause neurodegeneration, including AD?" (PMID 22329651, 2012). "Accordingly, the tight relationship between ghrelin and insulin also relies in the general assumption that insulin elicits a negative action on both plasma acylated- and unacylated-ghrelin concentration, while administration of acylated-ghrelin results in insulin resistance." (PMID 23162532, 2012). "Furthermore, the tissue specific manner of activins's function of modulating insulin sensitivity and insulin secretion may help identify the target tissue for prevention and management of T2D and insulin resistance." (PMID 23304117, 2012).
Insulin resistance (continued). "Based on published evidence that connects the function of the mitochondria with insulin resistance and T2D, we hypothesized that there are genes responsible for the crosstalk between the mitochondria and the insulin signaling system, which makes them good candidates for T2D." (PMID 23236286, 2012). "In keeping with recent work from Febbraio's group, we found that IL-6 deficient mice were more glucose and insulin intolerant than WT controls when fed a HFD, demonstrating that IL-6 may play a protective role against the development of insulin resistance in conditions of chronic nutrient excess." (PMID 23240005, 2012). "While AKT2 deficiency impairs insulin action on liver metabolism, elevated basal AKT activity contributes to insulin resistance in obese mice induced by HFD and elevated basal PI3K signaling is associated with insulin resistance in skeletal muscle and glucose intolerance in men." (PMID 22412882, 2012). "The differential risk associated with sulfonylurea and insulin also suggested that hyperinsulinemia or insulin resistance alone might not be responsible for thyroid cell proliferation in patients with type 2 diabetes." (PMID 23300866, 2012). "In addition, CRP was also correlated with fasting insulin and insulin resistance verified by HOMA." (PMID 21822486, 2012). "The stimulatory mechanism of protein synthesis is attributable to the stimulation of the ancestral pathway m-TOR-kinases independently by insulin: This pathway could mainly activated in conditions of insulin-resistance as can be seen during the course of chronic renal failure." (PMID 23227299, 2012). "We hypothesized that the induction of obesity in hypertensive rats would determine a cluster of dysfunctions enough to characterize the metabolic syndrome, as it is observed in humans, pointing out reduced expression of GLUT4 in insulin-sensitive tissues as a marker of insulin resistance." (PMID 22897936, 2012). "In the context of insulin resistance, manipulation of only a few specific miRNAs could potentially improve the efficacy of or suppress development of tolerance to pharmaceuticals traditionally used to improve glucose tolerance and insulin sensitivity." (PMID 22851965, 2012). "Since insulin has an inhibitory action on HMG-CoA reductase (3-hydroxy-3-methyl-glutaryl coenzyme A reductase), the key enzyme in cholesterol biosynthesis, insulin deficiency or insulin resistance may therefore be responsible for hyperlipidemia." (PMID 23267560, 2012). "We found that fasting serum insulin and HOMA-IR were clearly associated with lipocalin-2 even in stepwise regression analysis, suggesting that this protein might be an indicator for β cell function and insulin resistance in humans." (PMID 22292925, 2012). "The mechanisms for this association are unknown, but hyperinsulinaemia (a hallmark of insulin resistance) and the increase in bioavailable insulin-like growth factor I (IGF-I) appear to have a role in tumor initiation and progression in insulin-resistant patients." (PMID 22701472, 2012). "Physical activity could reduce insulin resistance and improve insulin sensitivity in adults." (PMID 22455464, 2012). "Moreover, TNF-α is known to directly inhibit insulin signaling, resulting in insulin resistance." (PMID 23155382, 2012). "T2MD is a chronic disease that is characterized by insulin resistance and Its development is directly associated with the inability of insulin to exert its action, not just on carbohydrate metabolism but also on primarily in lipid metabolism, in addition to its anabolic and anti-catabolic actions." (PMID 23067133, 2012). "Therefore, mtDNA mutations (or reduced mtDNA content) that result in lower levels of ATP production may influence both insulin secretion and glucose sensing, thus contributing to insulin resistance." (PMID 21298061, 2011). "Furthermore, it is possible that peripheral insulin resistance could decrease insulin transportation into the brain." (PMID 22389813, 2011).
Insulin resistance (continued). "However, CrPic was reported to enhance skeletal muscle glucose transporter-4 (GLUT-4) translocation and insulin sensitivity in a rat model of obesity and insulin resistance and also recruits intracellular localization of GLUT-4 to the cytoplasmic side of the plasma membrane of murine adipocytes." (PMID 21539728, 2011). "In patients with severe insulin resistance this could cause a vicious cycle where the progressive increase in insulin dosage cause a reduction in GLUT4 levels and thereby increase the need for further insulin treatment." (PMID 22114711, 2011). "Indeed, a relation between apoptosis and insulin resistance has been described before and recent studies have shown that apoptosis might be increased in insulin resistant liver in humans." (PMID 21843341, 2011). "The results support the possibility that, in vivo, the ability of palmitate to induce insulin resistance may include activating macrophages to secrete proinflammatory cytokines and chemokines that would negatively impact on insulin action in skeletal muscle, acting through novel PKC's." (PMID 22046423, 2011). "Altogether these findings could be crucial for fetal insulin modulation of endothelial-derived NO synthesis in human umbilical vessels from pregnancy diseases associated with hyperinsulinemia, such as GDM, and other states of insulin resistance." (PMID 22144986, 2011). "Moreover, an animal study also showed that amylin could suppress insulin secretion by enhancing β-cell apoptosis, which consequently induced hepatic and extrahepatic insulin resistance and glucose dysregulation in human IAPP transgenic rats." (PMID 21935471, 2011). "Former research has demonstrated divergent results regarding the relationship between insulin resistance and physical fitness in obese children and adolescents, and the effect of fitness on insulin may be mediated through a direct pathway and indirectly through changes in body composition." (PMID 21619652, 2011). "However, high physiological concentrations of insulin can substantially increase cellular mitogenic responsiveness to other growth factors and promote disadvantageous growth and proliferation, particularly in the presence of insulin resistance." (PMID 21668983, 2011). "The ability of insulin to suppress hormone-sensitive lipase --an enzyme responsible for adipocyte fatty acid release, which facilitates β-oxidation and ketone body production in the liver-- is also known to be affected by hyperthyroidism-induced insulin resistance." (PMID 21492449, 2011). "We postulate that early in the development of diet induced insulin resistance, a change in plasma FFAs may directly, through signaling at the level of β-cell, or indirectly, by decreasing hepatic insulin clearance, result in the observed hyperinsulinemic compensation." (PMID 21479217, 2011). "The uncoupling of obesity from insulin resistance, highlights the importance of tissue fatty acid composition for insulin sensitivity and further suggests that conversion of palmitate to stearate, and the desaturation of stearate to oleate are critical events for the emergence of insulin resistance." (PMID 21738729, 2011). "However, in the high milk consumption group, children experienced a decrease in insulin response after an oral glucose tolerance test indicating that milk may protect against insulin resistance." (PMID 22299005, 2011). "However, it is clear that the insulin resistance index was improved due to AX treatment as compared to the HF group, suggesting that the anti-obesity effect of AX was accompanied by a beneficial effect on insulin sensitivity." (PMID 21695273, 2011). "Therefore, since SHRSP is animal model shows insulin resistance, the decreasing of plasma glucose and insulin levels in both studies and HOMA-IR of single oral dose of L-Trp administration indicates that L-Trp supplementation contributes to increase insulin sensitivity of the rats." (PMID 21831334, 2011).
Insulin resistance (continued). "Because FFA-induced insulin resistance may play a key role in T2D, we have carried out a comprehensive study of the effects of FFA on the molecular mechanisms involved in insulin-resistance, insulin-regulated glucose and fat metabolism in rat liver cells in vitro." (PMID 22087313, 2011). "We expanded the knowledge about the lack of association between the polymorphism and insulin resistance investigating whether the PNPLA3 148M allele was associated with insulin sensitivity estimated from OGTT." (PMID 22140488, 2011). "In addition, it is known that insulin effect in patients with insulin resistance is improved by infusion of adenosine receptor agonists suggesting that insulin biological effects could be facilitated upon adenosine receptor activation." (PMID 22144986, 2011). "Knowing that about 3–15% of women develop gestational diabetes mellitus, characterized by insulin resistance and increased insulin secretion, our results could suggest that inhibition of OT neurons would, at least partly, be responsible for this insulin resistant state." (PMID 21980491, 2011). "In the presence of insulin resistance, serum insulin concentrations may exceed these levels." (PMID 22194983, 2011). "However, the women in the lowest quartile of physical activity had lower HDL (p = 0.05), Apo A1 (p = 0.005) and atheroprotective natural anti-PC (p = 0.016) and higher levels of insulin (p = 0.05) and higher frequency of insulin resistance than those in the highest quartile." (PMID 21235741, 2011). "Furthermore, studies have revealed that during a chronic insulin resistance state or chronic inflammation, insulin may aggravate inflammatory responses, increase markers of oxidative stress and lead to the formation of superoxide anions." (PMID 22654727, 2011). "Insulin resistance seen in RA, lupus and other autoimmune diseases could also be attributed to reduced vagal tone since, vagus has a regulatory role in insulin secretion and insulin resistance produced by bilateral cervical vagotomy can be reversed by acetylcholine." (PMID 21261967, 2011). "Thus, a dysfunction in adipose tissue growth may be a key factor in insulin resistance due to imbalanced fat storage and disrupted insulin action." (PMID 20107501, 2010). "At the cellular level, multiple regulatory mechanisms and metabolic pathways may contribute to the pathogenesis of insulin resistance, potentially mediated by alterations in insulin signaling, mitochondrial oxidative metabolism and ATP production, fatty acid oxidation, or proinflammatory signaling." (PMID 20369014, 2010). "In fact, a recent study suggests that the negative correlation between high molecular weight (HMW) adiponectinaemia and fasting insulin levels emerges between two and six years of age and only during this period could a condition of insulin resistance be evidenced." (PMID 20298581, 2010). "Also oxidative stress through TCF7L2/NF-kB/MAPK/HIF1A/SREBP regulatory cascade via insulin, MAPK and Calcium signaling pathways, may activate inflammatory responses than in turn causes insulin resistance." (PMID 20942928, 2010). "Thus, the reduction in glucose tolerance observed in F0-BPA10 mice compared with controls may reflect an inability to increase insulin levels enough to compensate for the observed increase in insulin resistance." (PMID 20488778, 2010). "Heightened flux through the HBSP leads to the onset of insulin resistance and the precise molecular basis by which this occurs is a topic of great interest since it could lead to clarity regarding the insulin-desensitizing effects of hyperglycemia." (PMID 20851343, 2010). "Differences were found between boys and girls in the relationships between risk factors (lipid profile, insulin resistance) and fitness by some authors and not by others; such differences were expected, due to the difference in insulin sensitivity between both sexes." (PMID 20652084, 2010).